RETNLB (resistin like beta)
Description:
Probable hormone.
Synonyms: FIZZ2; HXCP2; RELMb; FIZZ1; RELM-beta; RELMbeta; XCP2
Tractability: Antibody: UniProt places it where antibodies can reach, with medium confidence; UniProt predicts a signal peptide or a membrane-spanning region; its Gene Ontology location is reachable by antibodies, with medium confidence.
Gene: Protein-coding gene on chromosome 3 (108,743,424 to 108,757,410, reverse strand). Ensembl gene ENSG00000163515.
Subcellular location: Secreted
Subcellular location (Human Protein Atlas): Endoplasmic reticulum; Predicted to be secreted
Gene Ontology:
Molecular function: hormone activity
Biological process: epithelial cell proliferation; signal transduction
Cellular component: extracellular region
Genetic constraint (gnomAD): Loss-of-function variants: 7 observed, 6.03 expected, observed/expected ratio (o/e) 1.16, 90% interval 0.65 to 1.85. That is too few expected variants to judge how well the gene tolerates losing a copy. Missense variants: 111 observed, 106.4 expected, observed/expected ratio (o/e) 1.04, 90% interval 0.89 to 1.22. Synonymous variants: 43 observed, 43.72 expected, observed/expected ratio (o/e) 0.98, 90% interval 0.77 to 1.27.
Homologues: Orthologues: chimpanzee RETNLB (98% identical), macaque RETNLB (87% identical), pig RETNLB (69% identical), dog RETNLB (66% identical), mouse Retnlb (57% identical), rat Retnlb (57% identical), rat Retnlg (57% identical), mouse Retnlg (54% identical), mouse Retnla (50% identical), rat Retnla (49% identical). Paralogues in human: RETN (46% identical).
Diseases named in the same sentence as RETNLB in open-access papers:
RETNLB is named in the same sentence as 83 diseases in open-access papers, as found by Europe PMC text mining. Sharing a sentence is not in itself a finding about the gene and the disease. The quoted sentences say what the papers report.
colon cancer (7 papers, 2015 to 2024). "The intestinal goblet cell-specific protein RETNLB is markedly over-expressed in a human colon cancer cell line, and its expression is reportedly associated with histological grade of differentiation and lymph node metastasis in CRC patients." (PMID 33680920, 2020). "Additionally, RETNLB positivity in colon cancer was observed to be associated with lymph node metastasis and histological grade of differentiation, and led to a notably longer postoperative survival time." (PMID 34158059, 2021). "In tumors, previous reports have suggested that positive expression of RETNLB were detected in most tissues from gastric carcinoma and colon cancer patients, suggesting that the dysregulation of RETNLB may be valuable for the diagnosis of some cancers." (PMID 34158059, 2021). "Interestingly, we found that no report reported the RETNLA expression or function in cancers, but as early as a decade ago, positive RETNLB expression had been tested in 81.25% of 80 colon cancer patients, where there was a positively correlation between RETNLB expression and survival time." (PMID 34158059, 2021). "The curves present survival data for the two groups of colon cancer patients based on gene expression level (high or low) of SPINK4, RETNLB, ASRGL1, CLCA1, and FCGBP (rows)." (PMID 31337362, 2019).
gastric cancer (5 papers, 2017 to 2023). A primary or metastatic malignant neoplasm involving the stomach. "It is noteworthy that in gastric carcinoma, RETNLB levels are inversely related to patient survival." (PMID 36707698, 2023). "Previous detections have revealed that RETNLB-overexpression can promote the gastric carcinoma cells’ migration and invasion and facilitate the progression of epithelial-mesenchymal transition." (PMID 34158059, 2021). "Similarly, 65.4% of 136 human gastric carcinoma patients were positive for RETNLB expression, which led to a significantly longer overall survival than patients with negative RETNLB expression." (PMID 34158059, 2021). "Besides, functional experiments demonstrated that RETNLB-overexpression could remarkably enhance the invasiveness and mobility of gastric carcinoma cells and promote the progression of epithelial-mesenchymal transition." (PMID 34158059, 2021).
parasitic infections (5 papers, 2011 to 2022). "Although most studies on RETNLB have focused on its role in intestinal defense against parasitic infections and inflammation of the colon, its role in tumor biological functions is receiving increasing attentions." (PMID 34158059, 2021). "The probiotic treatment significantly increased mRNA expression of genes associated with enhanced protection against parasitic infection, including IL-25, RETNLB, and SOCS3, and did not interfere with the normal expulsion of L4 from the jejunum." (PMID 35335620, 2022).
abdominal aortic aneurysm (2 papers, 2017 to 2021). Enlargement and ballooning of the vessel that supplies arterial blood to the abdomen, pelvis and legs. "Moreover, reduced RETNLB level has been shown to suppress the formation of abdominal aortic aneurysm." (PMID 34158059, 2021).
colorectal cancer (2 papers, 2016 to 2023). A primary or metastatic malignant neoplasm that affects the colon or rectum. "RETNLB–RETNLB has been found to be overexpressed in ∼80% of colorectal cancer patients positively correlating with patient survival." (PMID 38304289, 2023).
dysplasia (2 papers, 2023). A usually neoplastic transformation of the cell, associated with altered architectural tissue patterns. "Indeed, RETNLB is expressed in the metaplastic epithelium of Barrett’s esophagus and enhanced in dysplasia, which can be served as a potential biomarker for such condition." (PMID 36707698, 2023).
oral squamous cell carcinoma (2 papers, 2021 to 2023). "Collectively, these evidences demonstrate that RETNLB deficiency suppresses the viability, mobility and invasiveness of oral squamous cell carcinoma cells partly by inactivating the TLR2/4/ERK signaling pathway." (PMID 34158059, 2021). "This study aimed to investigate the function and the underlying mechanism of resistin like beta (RETNLB) in oral squamous cell carcinoma." (PMID 34158059, 2021). "High expression of RETNLB was closely linked to age and pathological tumor, and significantly related to poor survival of oral squamous cell carcinoma patients." (PMID 34158059, 2021). "Moreover, the effect of RETNLB on the growth, migration and invasion of oral squamous cell carcinoma cells as well as the underlying mechanism were explored through biological experiments." (PMID 34158059, 2021). "Inspired by these findings, a series of functional tests were performed to illuminate the biological role of RETNLB in oral squamous cell carcinoma." (PMID 34158059, 2021). "Herein, we illustrated that RETNLB was up-regulated in oral squamous cell carcinoma and negatively correlated with the overall survival of patients with oral squamous cell carcinoma." (PMID 34158059, 2021). "Of note, in the oral squamous cell carcinoma cases examined, the expression of RETNLB was found to be positively correlated with age and pathological tumor (p < 0.05)." (PMID 34158059, 2021). "The biological role of RETNLB was only explored in oral squamous cell carcinoma cells, further animal experiments were required for verification." (PMID 34158059, 2021). "Altogether, these findings showed that silencing RETNLB inhibited the aggressive behaviors of oral squamous cell carcinoma cells in vitro." (PMID 34158059, 2021). "In conclusion, we described that RETNLB was upregulated in oral squamous cell carcinoma and led to a worse survival." (PMID 34158059, 2021). "Before elucidating the functional role of RETNLB in oral squamous cell carcinoma, CAL27 and TCA-83 cells were transfected with si-RETNLB#1 and si-RETNLB#2 to down-regulate the expression of RETNLB." (PMID 34158059, 2021). "The data of oral squamous cell carcinoma samples from The Cancer Genome Atlas database was used to examine RETNLB expression and assess its correlation with the clinical outcomes." (PMID 34158059, 2021). "In the present study, we investigated the expression and prognostic value of RETNLB in oral squamous cell carcinoma patients through bioinformatics analysis of the data from The Cancer Genome Atlas database." (PMID 34158059, 2021). "Analogously, the numbers of colonies of si-RETNLB-transfected CAL27 and TCA-83 cells were significantly less than si-NC-transfected cells, suggesting that RETNLB knockdown reduced the colony-forming capacities of oral squamous cell carcinoma cells." (PMID 34158059, 2021). "Mechanistically, RETNLB possibly affects the phenotypes of oral squamous cell carcinoma cells partly by modulating the TLR2/4/ERK signaling pathway." (PMID 34158059, 2021). "Together, all these data demonstrated that RETNLB may have a prognostic value in oral squamous cell carcinoma." (PMID 34158059, 2021). "In the present study, the abnormal expression of RETNLB was also found in 338 oral squamous cell carcinoma tissues compared to paratumor tissues based on data from The Cancer Genome Atlas, hinting its involvement in oral squamous cell carcinoma." (PMID 34158059, 2021). "These detections demonstrated that downregulation of RETNLB suppresses the progression of oral squamous cell carcinoma cells might by inactivation of the TLR2/4/ERK pathway." (PMID 34158059, 2021). "All these findings support that RETNLB might be a valuable prognostic biomarker in oral squamous cell carcinoma patients, and implying that further exploration of RETNLB’s role in oral squamous cell carcinoma is necessary." (PMID 34158059, 2021). "We found that RETNLB was upregulated in oral squamous cell carcinoma tissues and cells." (PMID 34158059, 2021).
oral squamous cell carcinoma (continued). "Collectively, the data indicated that downregulation of RETNLB may suppress the tumor growth in oral squamous cell carcinoma." (PMID 34158059, 2021). "All these data suggested that RETNLB may be a novel bio-target for the therapeutic intervention of oral squamous cell carcinoma." (PMID 34158059, 2021). "Nevertheless, the results in two cell lines and the bioinformatics analysis based on the public database unanimously illustrating the positive role of RETNLB in oral squamous cell carcinoma cell malignant development and the predictive potential on prognosis of oral squamous cell carcinoma patients." (PMID 34158059, 2021). "Thus, western blot assay was used to verify our suspicion that RETNLB played the tumor-promoting effect in oral squamous cell carcinoma cells through regulating the TLR2 and TLR4." (PMID 34158059, 2021). "Moreover, functional experiments verified that the down-regulation of RETNLB inhibited the growth and movement-related phenotypes of oral squamous cell carcinoma cells." (PMID 34158059, 2021). "Furthermore, we revealed that RETNLB acted a promoting role in the malignant development of oral squamous cell carcinoma cells via regulating TLR2/4/ERK pathway." (PMID 34158059, 2021). "The data suggested that depletion of RETNLB exhibited an inhibitory effect on the cells growth, invasion and migration, which provided a basis for demonstrating that targeting RETNLB may restrain the progression of oral squamous cell carcinoma." (PMID 34158059, 2021). "These evidences suggest that RETNLB is expected to be a potential biomarker in some tumors, and led us to suspect that RETNLB may also play a role in oral squamous cell carcinoma, which has not yet been reported." (PMID 34158059, 2021). "Consistently, RETNLB was observed to be overexpressed in two commonly used oral squamous cell carcinoma cell lines in comparison with non-tumor cell line (p < 0.01), suggesting that RETNLB might play a carcinogenic effect in oral squamous cell carcinoma." (PMID 34158059, 2021).
metastatic cancers (1 paper, 2023). A carcinoma which has spread from the original site of growth to another anatomic site. "The metastatic cancers that responded to FOLFOX had reduced expression of RETNLB compared to non-responders (logFC = −2.07)." (PMID 38304289, 2023).
infection (49 papers, 2002 to 2025). The state of being infected such as from the introduction of a foreign agent such as serum, vaccine, antigenic substance or organism. "Of the 10 annotated up-regulated genes in SL1344 infection at 8 hours, RETNLB as a colon-specific gene has been reported to associate with bacteria infection, and RETNLB in situ hybridization occurs in proliferative mouse epithelial cells." (PMID 21172007, 2010). "When looking at the effects of infection on expression of immune-related genes in the proximal colon we found an upregulation of genes related to type-2 responses such as CCL26, CCR4, and RETNLB (fold changes 1.4, 1.5 and 1.4, respectively)." (PMID 38081984, 2023). "qPCR analysis demonstrated that for genes that were affected either by infection challenge (e.g. AGR2, G6PC, RETNLB) or diet (e.g. IL1R2, CD3G, ADH1C), gene expression levels of the microarray were verified." (PMID 21698235, 2011). "In particular, the expression of IL13 and RETNLB was significantly increased in infected pigs, regardless of diet (main effect of infection with a fold change of 3.7 and 1.7, respectively), and the expression of CCL26, IL10 and TFF2 also tended to be increased." (PMID 38081984, 2023).
tumor (46 papers, 2011 to 2026). "The evidences supporting this view are that the overall survival rate of patients with low RETNLB expression was significantly longer than that of high RETNLB expression patients, and RETNLB was found to be associated with pathological tumor and age." (PMID 34158059, 2021). "In lung cancer, silencing TLR2, TLR4, and TLR9, along with epithelial-specific MyD88/NF-κB signaling, significantly reduces the expression of pro-tumor immunosuppressive factors like RETNLB, while enhancing the expression of anti-tumor cytokines like IFN-γ." (PMID 41200171, 2025). "Seven hub genes, REG4, S100A7, CLCA1, FABP4, RETNLB, SFRP2, and WNT10A, were all significantly associated with CC patient prognosis and differentially expressed in normal and tumor tissues." (PMID 36941538, 2023).
inflammation (7 papers, 2014 to 2022). Aberrant reaction of the microcirculation characterized by movement of fluid and leukocytes from the blood into extravascular tissues. "Moreover, colonic inflammation resulted in a decrease of TFF3 and RETNLB expression, indicating a dysfunction in goblet cells." (PMID 35252301, 2022).
cancer (5 papers, 2021 to 2023). A tumor composed of atypical neoplastic, often pleomorphic cells that invade other tissues. "However, with the in-depth studies, subsequent reports demonstrated that RETNLB also plays a role in several research areas, such as inflammatory disease, cancer, and metabolic function." (PMID 34158059, 2021). "RT-qPCR showed the expression of CHI3L1, IL-10, RETNLB (Fizz1), and Arg1, to confirm the M2 macrophages The results showed that the expression level of both CD68 and CD206 were significantly increased in cancer tissues compared with paracancerous tissues." (PMID 35637970, 2022).
endocrine system disorder (1 paper, 2010). A disease involving the endocrine system. "IPA data base showed RETNLB and FDPs were associated with endocrine system disorders; CAPG, ACOT9, FDPS, and IMPDH2 were associated with genetics disorder." (PMID 21172007, 2010).
RETNLB also shares sentences with these, for which no sentence is quoted: colitis (27 papers); asthma (21); lung fibrosis (12); helminth infection (10); Insulin resistance (7); Obesity (7); pulmonary hypertension (7); bacterial infection (6); nematode infection (6); allergic asthma (5); eosinophilia (5); scleroderma (5); Sepsis (5); fibrosis (4); atherosclerosis (3); enteritis (3); glioma (3); intestinal infections (3); liver fibrosis (3); lung diseases (3); viral infection (3); allergic disease (2); aneurysm (2); chronic asthma (2); endotoxemia (2); Granuloma (2); hyperlipidemia (2); infectious colitis (2); lymph node metastasis (2); mastocytosis (2).
A further 40 diseases each share a sentence with RETNLB in 2 papers or fewer.